MCU (mitochondrial calcium uniporter)
Diseases named in the same sentence as MCU in open-access papers (continued):
Sharing a sentence is not in itself a finding about the gene and the disease.
periodontitis (1 paper, 2026). An acute or chronic inflammatory process that affects the tissues that surround and support the teeth. "The mitochondrial Ca2+ channel proteins, voltage dependent anion channel 1 (VDAC1) and mitochondrial calcium uniporter (MCU), were significantly upregulated in periodontitis gingiva, and their expression positively correlated with probing depth." (PMID 42196298, 2026).
polycystic ovary syndrome (1 paper, 2021). A disorder that manifests as multiple cysts on the ovaries. "Metformin also has been reported to increase VDAC1 expression levels in NCaP cells along with increased the levels of IP3R1, IP3R2, IP3R3, and MCU mRNA, as well as VDAC1 protein, and in polycystic ovary syndrome (PCOS)-like rats treated with metformin." (PMID 34671273, 2021).
renal cell carcinoma (1 paper, 2023). "Similarly, the reduction of MCU expression in renal cell carcinoma, through the overexpression of the EF-hand domain family member D1 protein (EFHD1), and a negative regulator of MCU activity, leads to the reduction in cell migration and metastatic potential." (PMID 37759703, 2023).
Sensorineural hearing impairment (1 paper, 2018). A type of hearing impairment in one or both ears related to an abnormal functionality of the cochlear nerve. "Since the CD1 strain has sensorineural hearing impairment at high frequencies, we measured ABRs weekly from 4 weeks to 7 weeks of age for both MCU knockouts and wild-type littermates." (PMID 30670946, 2018).
Skeletal muscle atrophy (1 paper, 2017). The presence of skeletal muscular atrophy (which is also known as amyotrophy). "Interestingly, recent studies from other research groups also provided evidence of MCU-dependent mitochondrial Ca2+ uptake in protecting denervation-induced skeletal muscle atrophy by using virus-mediated overexpression of MCU." (PMID 28395670, 2017).
sleeping sickness (1 paper, 2020). "The mitochondrial calcium uniporter (MCU) is essential for the regulation of oxidative phosphorylation in mammalian cells, and we have shown that in Trypanosoma brucei, the etiologic agent of sleeping sickness, this channel is essential for its survival and infectivity." (PMID 32184243, 2020).
Stroke (1 paper, 2015). Sudden impairment of blood flow to a part of the brain due to occlusion or rupture of an artery to the brain. "Therefore, the inhibition of the activity of MCU or disruption of VDAC1-MCU interaction might be a strategy to stroke and degenerative diseases." (PMID 25753332, 2015).
type 2 diabetes (1 paper, 2022). "Additional studies indicate that a loss of function in mitochondrial Ca2+ flux proteins, MCU and NCLX have been observed in some type 2 diabetes patients." (PMID 35805078, 2022). "The MCU protein is currently being examined as a target for pharmacological activation in patients with type 2 diabetes (T2D)." (PMID 35805078, 2022).
Ventricular arrhythmia (1 paper, 2021). "Our work indicates that MCU, the major protein responsible for rapid uptake of mitochondrial calcium, has an important role in the pathophysiology of ventricular arrhythmia and repolarization abnormalities after high-fat diet." (PMID 34497331, 2021).
ventricular fibrillation (1 paper, 2020). A disorder characterized by an electrocardiographic finding of a rapid grossly irregular ventricular rhythm with marked variability in QRS cycle length, morphology, and amplitude. "A study utilizing a knockout MCU mouse model found, in a non-ischemic HF setting, MCU knockout mice display a shorter AP duration and fewer incidences of EADs and ventricular fibrillation when compared to control animals." (PMID 33013458, 2020).
ventricular tachycardia (1 paper, 2021). A disorder characterized by an electrocardiographic finding of three or more consecutive complexes of ventricular origin with a rate greater than a certain threshold (100 or 120 beats per minute are commonly used). "MCU KO mice are protected from HFD-induced long QT, inducible ventricular tachycardia, and abnormal ventricular repolarization." (PMID 34497331, 2021).
cancer (56 papers, 2014 to 2025). A tumor composed of atypical neoplastic, often pleomorphic cells that invade other tissues. "Dysregulation of MCU is implicated in various diseases, such as neurodegenerative disorders, cardiac diseases, and cancer." (PMID 39921279, 2025). "Multiple Ca2+-handling proteins, including CACNA1D, CACNA2D1, TRPV4, TRPV1, TRPM4, MCU, and RyR1, exhibit cancer-associated overexpression or functional changes, correlating with poor prognosis and aggressive disease features." (PMID 41226294, 2025). "This drug was selectively cytotoxic to cancer cells and caused an increase in the expression of MCU which led to Ca2+ overload and in turn cell death in TNBC cells." (PMID 38538285, 2024). "To explore the role of MCU in cell chemotaxis and extracellular matrix invasion, processes associated with cancer metastasis in which Ca2+ signaling has been proposed to play a role, we employed a transwell-invasion assay." (PMID 37363724, 2023). "While the deregulation of expression varies in a cancer type-specific manner, in general, overexpression of MCU and loss of MICU1 expression are correlated with poor prognosis." (PMID 35490194, 2022). "Conversely, also MCU complex reduced expression or activity has been associated with cancer cell death." (PMID 30011966, 2018). "This review will summarize the molecular structure of MCU, the regulatory mechanisms underlying its activity, and will uncover its role in pathophysiology, with particular attention to cancer biology." (PMID 28740830, 2017). "Downregulation of MCU by miR-25 suppresses mitochondrial Ca2+ uptake, causing apoptotic resistance and favoring cancer cell survival." (PMID 25897426, 2015). "Finally, we report that deletion of MCU in cancer cells caused a marked reduction in tumor growth in multiple cancer models." (PMID 37502961, 2023). "However, identifying the mechanism by which MCU is implicated in the metabolic shift during cancer progression requires further investigation." (PMID 29137386, 2017). "miR-25-dependent MCU downregulation has also been observed in pulmonary artery smooth muscle cells, where decreases in mitochondrial Ca2+ levels cause the activation of a cancer-like phenotype characterized by increased cellular proliferation, migration, and apoptotic resistance." (PMID 33171939, 2020). "Of note, forced reliance of HEK MCU-KO on the TCA cycle caused a reduction of ATP levels, activation of AMPK and a bioenergetic crisis that led to cell death, similar to the responses of cancer cells to acute deletion of either MCU or InsP3R." (PMID 37363724, 2023). "Similar results have been obtained in other types of cancer, meaning that deregulation of MCU plays an important role in carcinogenesis including BC." (PMID 37885995, 2023). "MCU deletion inhibited cancer stem cell-like spheroid formation and cell invasion in vitro, both predictors of metastatic potential." (PMID 37363724, 2023). "Specifically, the inhibition of mCa2+ entry by cancer-related miR-25 represents the first evidence for the regulation of MCU by miRNA and offers preliminary clues to the significance of miRNAs in regulating mCa2+ entry." (PMID 36013278, 2022). "In some cancers, MCU overexpression protects cells from apoptosis and thus MCU silencing potentiates cell death." (PMID 35490194, 2022). "The mitochondrial calcium uniporter (MCU) is known to enhance aerobic glycolysis in cancer; however, we recently showed that MCU regulated metabolic reprogramming to FAO, in part, by increasing expression and activity of Cpt1a." (PMID 34413485, 2022). "Knockdown of MCU in respective cancer cells resulted in decreased migration an invasion, potentiation of compound-induced cell death and metabolic restructuring." (PMID 33614647, 2021). "Consistent with the complex biology of MCU (Section 2.1), both pro- and anti-tumorigenic roles of MCU have been reported in cancers." (PMID 34069047, 2021).
cancer (continued). "On the other hand, MCU is a target for miR-25, which is highly expressed in cancers and cancer cell lines, and downregulation of MCU through miR-25 increases resistance to apoptosis in PC3 and HCT116 cells." (PMID 34069047, 2021). "The crucial role of MCU regulators in cancer progression gets also obvious by the impact of MICU1 impairment, which results in the opening of MCU, enhanced mitochondrial Ca2+ uptake and ROS production in HeLa, and potentially boosts tumor growth." (PMID 33614647, 2021). "The effect of MCU-KO on enhanced NFAT activity in cancer cells and proliferative smooth muscle cells is likely largely offset by the disruption of mitochondrial metabolism as a result of MCU loss." (PMID 34499925, 2021). "The expression of MCU was found to be upregulated in several cancer types including breast cancer and liver cancer." (PMID 33614647, 2021). "HINT2 therefore sensitizes cells to apoptosis by altering the expression of MCU regulators, while cancer cells suppress this by downregulating HINT2 expression." (PMID 32059571, 2020). "An example is the activity of mitochondrial transporters VDAC and MCU, which have been found to be responsible for aberrant metabolism that supports cancer progression and therapy resistance." (PMID 33282859, 2020). "Depletion of MCU expression also reduces ROS production and deregulates hypoxia-inducible factor 1 alpha, diminishing cancer progression." (PMID 33511135, 2020). "Previous studies indicated that the MCU complex possesses distinct functions in different types of cancer." (PMID 32371956, 2020). "MCU is overexpressed in several cancers such as colorectal, ovarian, prostate, and breast cancer, and is associated with genetic alterations as gene amplifications." (PMID 33233365, 2020). "Several recent studies have contributed to our understanding of the molecular foundations of the MCU complex in the regulation of Ca2+ influx into mitochondria, as well as its implication in cancer progression." (PMID 33114428, 2020). "In most cancers levels of MCU are elevated, and while regulation of MCU expression has not been widely studied, the Cancer Genome Atlas (TCGA) demonstrates that the MCU gene is amplified in some tumor types." (PMID 32059571, 2020). "Independently of the role of MCU in cancer cell migration, different studies have highlighted the role of mitochondrial Ca2+ homeostasis in immune cell polarization and chemotaxis." (PMID 28495532, 2018). "Several reports relate MCU overexpression or enhanced activity to cancer development and progression." (PMID 30011966, 2018). "Considering the up-regulation of both IP3R and MCU in several types of cancer cells, it seems that ER/mitochondria communication is key for increased mitochondrial metabolism and cancer progression." (PMID 30298016, 2018). "Mitochondrial calcium uniporter (MCU), a key ion channel that mediates Ca2+ uptake into mitochondria, was found to promote cancer progression and metastasis." (PMID 29137386, 2017). "Both IP3R and MCU are overexpressed in several cancer cell types, and the inhibition of the Ca2+ communication between these two organelles causes proliferation arrest, migration decrease, and cell death through mechanisms that are not fully understood." (PMID 28944215, 2017). "Assessment of [Ca2+]m uptake, migration and invasion, glucose uptake, ATP levels, LDH levels, and lactate production confirmed that miR-340 directly targets MCU to inhibit both cancer cell migration and invasion and glycolysis." (PMID 29137386, 2017). "For instance, several potential miR-25’s targeted genes have been identified thus far in cancer cells, including the apoptosis protein Bim and mitochondrial calcium uniporter." (PMID 29029434, 2017). "One of the first reports investigating the role of MCU in cancer progression identified miR-25 as a cancer-related MCU-targeting miRNA family." (PMID 28740830, 2017).
cancer (continued). "Intriguingly, MCU silencing partially decreased celastrol-induced cancer cell death, supporting the view of a deleterious effect of Ca2+ uptake in stress conditions." (PMID 28740830, 2017). "In conclusion, our work points out MCU as a critical checkpoint of metastatic behavior, and thus a potential pharmacological target in aggressive cancers, such as TNBC." (PMID 27138568, 2016). "Other studies implicate MCU-dependent clearance of cytoplasmic Ca2+ and Ca2+-sensitive CamKII activation in the regulation of cancer cell proliferation, as well as inactivation and nuclear-translocation of the transcription factor NFAT implicated in cell survival, angiogenesis, and invasion." (PMID 37363724, 2023). "Similarly, the mitochondrial calcium uniporter (MCU), a key Ca2+ channel implicated in the progression of multiple cancer types, reportedly enhances angiogenesis in the metastatic niche of BC through the downregulation of miR-4488 in BC-derived EVs." (PMID 37670020, 2023). "Importantly, the highly-similar effects of MCU deletion in isogenic fibroblasts on cell proliferation in vivo and in vitro in the present study strongly suggests that MCU is essential for cancer cell proliferation, particularly in tumorigenesis." (PMID 37363724, 2023). "Although the biological role of MCU in the progression of several cancer types has been studied, it remains unclear whether MCU is involved in BC cell metastasis via the regulation of autophagy." (PMID 37885995, 2023). "However, in cancer cells, polyamine synthesis inhibition increased the expression of both MCU and VDAC3." (PMID 36900391, 2023). "Therefore, we can induce the apoptosis in cancer cells by reducing MCU protein levels and mitochondrial Ca2+ uptake." (PMID 35743109, 2022). "In this pathway, MICU1 induces the accumulation of mitochondrial Ca2+ and the production of ROS, suggesting that the binding of MICU1 to the MCU is necessary for the function of the MCU complex and the entry of Ca2+ into mitochondria is a prerequisite survival factor of cancer cells." (PMID 35743109, 2022). "However, the current knowledge regarding the role of MCU in cancer is incomplete, and the molecular mechanisms involved and controlled by the Ca2+‐transporting complex are not fully understood." (PMID 36156348, 2022). "Notably, global genomic analysis identified loss of heterozygosity for MCU and MICU1 in human pancreatic cancer tissues, hinting to an involvement of these genes in cancer progression." (PMID 33614647, 2021). "It is clear that the role and regulation of MCU and its regulators is likely cancer-type specific." (PMID 32059571, 2020). "Similarly, expression of the MCU regulator mitochondrial calcium uniporter regulator 1 (MCUR1) stimulates ROS-mediated cancer cell migration and survival, accelerating tumor growth." (PMID 33282859, 2020). "In recent studies, altered MCU expression has been reported in cancer cells, and increased expression of MCU and alterations in proteins that regulate MCU channel activity have been associated with increased mtCa2+ and downstream effects that contribute to proliferation and tumor progression." (PMID 32914752, 2020). "Indeed, its overexpression reduces the expression of MCU, mitochondrial Ca2+ uptake, and the resistance of cancer cells to apoptotic challenges, thus, favoring tumor cell survival." (PMID 33233365, 2020). "In addition to miR-25, the authors also identified miR-138 as a regulator of MCU expression and demonstrated that nebulizing anti-miR-25 and miR-138 restored MCU expression and abolished the cancer-like phenotype." (PMID 33171939, 2020). "Based on these observations, the targeting of MCU channel for cancer therapy may be an intriguing option, especially for cancer patients who overexpress the MCU protein." (PMID 33171939, 2020). "Finally, mitochondrial Ca2+, and thus MCU activity, in overcoming cancer cell resistance to TNF-related apoptosis-inducing ligand (TRAIL) cytotoxicity has been recently observed." (PMID 30011966, 2018).
cancer (continued). "The molecular identification of the SOCE and MCU machinery, the introduction of powerful molecular tools, and the evolution of cancer genetics have all contributed to developing our understanding of how Ca2+ signals regulate cancer cell invasion and metastasis." (PMID 28848710, 2017). "Therefore, studies aimed at further delving into the role of mitochondrial Ca2+ homeostasis in pathophysiology, including cancer progression, were conducted based on the molecular modulation of the MCU complex components." (PMID 28740830, 2017). "Our results suggest that targeting MCU may have therapeutic implications in cancer." (PMID 37363724, 2023). "Besides, cancer cells tune their mitochondrial Ca2+ uptake very tightly by alterations in the expression and function of proteins involved in mitochondrial Ca2+ uptake and extrusion, including MCU, MICU1, MICU2, MCUR1, and NCLX." (PMID 33614647, 2021). "Specifically, DFMO treatment upregulated the expression of MCU and VDAC3, indeed reversing the effects of cancer in the case of VDAC3." (PMID 36900391, 2023). "Previous studies have confirmed that, in HCC, MCU gene inactivation can inhibit the metabolism of HCC cells, which in turn leads to decreased HCC cell proliferation and reduced cancer metastasis." (PMID 33114428, 2020). "In a variety of cancers, these 4 up-regulated genes (DNAJB1, MCU, MPRIP and PSAP) have been reported to be related to drug-resistance processes, cell death, cancer invasion and metastasis." (PMID 29285248, 2017). "In 38 tumor-specific SE-associated genes, 37 genes showed significantly elevated expression in at least 1 cancer cell line, including DNAJB1, MCU, MPRIP and PSAP." (PMID 29285248, 2017). "Previously, we reported that mitochondrial calcium uniporter (MCU) increases mitochondrial Ca2+ entry and ROS to impact cancer cell motility." (PMID 29137386, 2017). "Furthermore, overexpression of miR-25 dramatically decreased the levels of mitochondrial calcium uniporter (MCU) expression, hindered mitochondrial Ca2+ uptake, and prevented apoptosis in cancer cells." (PMID 37759744, 2023). "Mitochondrial calcium uniporter regulator 1 (MCUR1) functions as a scaffold factor by binding to mitochondrial calcium uniporter (MCU) and essential MCU regulator (EMRE), and plays a crucial role in mitochondrial Ca2+ absorption and ATP production in cancer cells." (PMID 36071480, 2022). "MCU and MICU1 deregulations have been reported in several cancers." (PMID 35490194, 2022). "Indeed, studies have shown that increased or decreased MCU and MICU1 expression in different cancers contribute to tumourigenesis and metastasis in several ways." (PMID 35490194, 2022). "In triple-negative breast cancer (TNBC), MCU silencing disturbs calcium uptake, enhancing alternative pathways such as SOCE, whereas the reduction of mitochondrial calcium levels inhibits cell migration in cancer cell lines." (PMID 33511135, 2020). "In addition, MCU deletion impairs tumor growth and metastasis formation and inhibits ROS production and HIF‐1α expression, two major triggers of cancer progression." (PMID 27138568, 2016). "Nevertheless, the roles of MCU-mediated Ca2+ influx in cancer cells remain unclear, in part because of a lack of genetic models." (PMID 37363724, 2023). "Our data show targeting MCU channels may not be a reliable therapeutic option in treating all cancers." (PMID 24802861, 2014). "Thus, our findings propose that MCU is intricately involved in the immune infiltration of BRCA and could potentially serve as a prognostic biomarker for assessing the immune response in these cancers." (PMID 38632642, 2024).